UGT1A1 (UDP glucuronosyltransferase family 1 member A1)
Diseases named in the same sentence as UGT1A1 in open-access papers (continued):
Sharing a sentence is not in itself a finding about the gene and the disease.
Hyperbilirubinemia (continued). "In our patient, the clinical presentation of fluctuating unconjugated hyperbilirubinemia prompted us to investigate the status of the UGT1A1 gene." (PMID 39996891, 2025). "For instance, fumonisin B1 competes with bilirubin for UGT1A1, leading to hyperbilirubinemia due to enzyme activity inhibition by substrate competition." (PMID 41154525, 2025). "Allele frequencies analysis revealed that the rs4148323 A allele in UGT1A1 gene and the allele C of SLCO1B3-rs2417940 were associated with hyperbilirubinemia (OR 2.897, p = 0.001 and OR 2.726,P = 0.001, respectively)." (PMID 38279097, 2024). "Two haplotypes of UGT1A1 were associated with hyperbilirubinemia susceptibility, of which ACG (OR 3.122, p = 0.001) was discovered to increase the risk of hyperbilirubinemia while GCG (OR 0.523, p = 0.018) reduced the risk." (PMID 38279097, 2024). "This functionality is how phenobarbital, a drug that enhances the expression of UGT1A1 in the liver, was historically used as an effective treatment for hyperbilirubinemia." (PMID 38474028, 2024). "We found that oral administration of iAs to neonatal hUGT1 mice that display severe neonatal hyperbilirubinemia leads to induction of intestinal UGT1A1 and a reduction in total serum bilirubin values." (PMID 36720308, 2023). "Increased erythrocyte turnover leads to increased bilirubin production, and the delayed activation of UGT1A1 in newborns can lead to hyperbilirubinemia." (PMID 38033855, 2023). "The absence of murine Ugt1a1 and the delayed expression of the human UGT1A1 transgene results in severe neonatal hyperbilirubinemia in hUGT1 mice during the suckling period." (PMID 36720308, 2023). "Glucuronidation mediated by UGT1A1 is an essential step in bilirubin metabolism, and UGT1A1 polymorphisms result in elevated serum UCB levels, known as hyperbilirubinemia." (PMID 37760555, 2023). "BIC is substrate for cytochrome P450-3A4 (CYP3A4) and uridine diphosphate glucuronosyltransferase 1 family, polypeptide A1 (UGT1A1), but the mechanism of hyperbilirubinemia, though looks similar to cabotegravir, remains to be defined." (PMID 36691090, 2023). "Decreased UDP-glucuronosyltransferase 1A1 (UGT1A1) enzyme activity leads to the unconjugated hyperbilirubinemia seen in Gilbert’s disease." (PMID 37474940, 2023). "Similarly, unconjugated hyperbilirubinemia may be caused by drugs interfering with the bilirubin uptake or conjugation such as antibiotics or drugs used for the management of pain during the post-operative phase which inhibit the UGT1A1 enzyme." (PMID 38155193, 2023). "Our lead SNV, rs6744284, was closely correlated to all GS-related variants assessable in our investigational setting – including UGT1A1*28 – and was the best predictor of hyperbilirubinemia in our patients." (PMID 36639636, 2023). "Of importance, the role of the intestinal tract and activation of the UGT1A1 gene in controlling the onset and development of neonatal hyperbilirubinemia has been clearly documented." (PMID 36720308, 2023). "In patients with hyperbilirubinemia with low UGT1A1 activity, UGT1A1 enhances the metabolism of UGT1A9 for the anticancer drug sorafenib." (PMID 36741721, 2022). "In summary, it has been discovered that antisense morpholinos targeting hepatic UGT1A1 generate physiological unconjugated hyperbilirubinemia serum." (PMID 36295901, 2022). "Some studies showed that UGT1A1 was more important in females than males for developing prolonged hyperbilirubinemia due to the higher expression of UGT1A1 in the female liver." (PMID 36605758, 2022). "A recent study from Malaysia revealed that Jaundiced neonates with severe neonatal hyperbilirubinemia were detected with genetic mutant UGT1A1*27 (c.686C>A)." (PMID 36128448, 2022). "The findings of this genetic association study suggest that UGT1A1 and PNPLA3 were associated with increased risk of hyperbilirubinemia and elevated ALT and AST levels in independent multinational and ancestrally diverse cohorts treated for ALL." (PMID 36580335, 2022).
Hyperbilirubinemia (continued). "In the current study, we used morpholino antisense oligonucleotides to suppress hepatic UGT1A1 and induce mild hyperbilirubinemia in mice." (PMID 36295901, 2022). "It has been reported that many tyrosine kinase inhibitors have lower IC50 values than their clinical steady-state maximum concentrations in UGT1A1 inhibition assays in vitro, in contrast showing a higher incidence of hyperbilirubinemia in vivo experiments." (PMID 36741721, 2022). "Several mutations of bilirubin uridine diphosphate-glucuronosyltransferase gene (UGT1A1) have been reported in patients with unconjugated hyperbilirubinemia." (PMID 35436954, 2022). "As a result of hyperbilirubinemias, the daily dose of nilotinib for patients with UGT1A1*6/*6 or *6/*28 genotypes is approximately 300–400 mg/day, lower than for patients with UGT1A1 *1/*1, *1/*6, *1/*28, or *27/*28 genotypes (600 mg/day)." (PMID 36294746, 2022). "Surprisingly, the effects of UGT1A1 impairment/hyperbilirubinaemia on sterol metabolism were mostly specific to female animals with only minor effects in male Gunn rats." (PMID 35156712, 2022). "Although this study clearly describes the functional impact of hyperbilirubinaemia/UGT1A1 dysfunction on sterol excretion, the mechanism explaining this effect remains to be elucidated." (PMID 35156712, 2022). "Abstract figure legend Female Gunn rats have an unconjugated hyperbilirubinaemia because of dysfunctional UGT1A1 enzyme function." (PMID 35156712, 2022). "Considering that male animals are unlikely to experience the confounding effects of oestrogen metabolism, the effect of UGT1A1 inhibition and hyperbilirubinaemia, should be clearer in these animals." (PMID 35156712, 2022). "Several mutations of the bilirubin uridine-diphosphate-glucuronosyltransferase gene (UGT1A1) have been reported in patients with unconjugated hyperbilirubinemia." (PMID 35436954, 2022). "This article emphasizes the importance of UGT1A1*6 in prolonged jaundice, especially for severe hyperbilirubinemia in Chinese term infants." (PMID 36605758, 2022). "In this study, the correlation between hyperbilirubinemia and two genes, SLCO1B1 and UGT1A1 variants were investigated in Thai neonates." (PMID 35501760, 2022). "Mild unconjugated hyperbilirubinemia in mice was induced by using specific morpholino antisense oligonucleotides to target hepatic UGT1A1, the enzyme responsible for bilirubin conjugation in the liver." (PMID 36295901, 2022). "This study aims to explore the correlation of the genetic variant of the two genes, UGT1A1 and SLCO1B1 causing hyperbilirubinemia in Thai newborns." (PMID 35501760, 2022). "Animals with moderate hyperbilirubinemia from partial knockdown of hepatic UGT1A1 showed improvements in glomerular filtration rate, renal blood flow, and renal vascular resistance." (PMID 36295901, 2022). "The incidence rates of hazardous and severe hyperbilirubinemia in the ABO HDNs were compared in different types of UGT1A1 genotype." (PMID 34074250, 2021). "More and more evidence has shown that the genetic variation of UGT1A1 is also closely related to the incidence rate and severity of neonatal hyperbilirubinemia." (PMID 34074250, 2021). "Reproducing results in larger study cohorts specifically designed to assess the impact of UGT1A1 on pazopanib or nilotinib-induced hyperbilirubinemia would further validate UGT1A1 as a pharmacogenetic biomarker for these drugs." (PMID 33805415, 2021). "Induction of UGT1A1 was one of the underlying mechanisms of treatment with phenobarbital, a CAR agonist used as a standard treatment for neonatal hyperbilirubinemia before the introduction of phototherapy and used in Crigler-Najjar syndrome type 241." (PMID 34045606, 2021). "Single patient case reports have described similar findings of severe nilotinib-induced hyperbilirubinemia among UGT1A1 PMs." (PMID 33805415, 2021).
Hyperbilirubinemia (continued). "Increased heme due to high hemoglobin levels, insufficient activity of UGT1A1, and immature gut microbiota are considered to be the factors of potential hyperbilirubinemia in newborns." (PMID 34940645, 2021). "For UGT1A1 NMs, IMs, and PMs, high-grade hyperbilirubinemia occurred at 6%, 12%, and 48%, respectively." (PMID 33805415, 2021). "For example, UGT1A1 is responsible for the metabolism of bilirubin, and a polymorphic variant UGT1A1*28 results in reduced UGT activity and, consequently, unconjugated hyperbilirubinemia, a condition known as Gilbert’s syndrome." (PMID 33573276, 2021). "In this study, we demonstrated that UGT1A1 mutation and polymorphism play an active role in the pathogenesis of ABO hemolysis-related neonatal hyperbilirubinemia." (PMID 34074250, 2021). "In the current study of hyperbilirubinemia group with G6PD deficiency, we showed that 6 cases were UGT1A1 c.211G > A homozygous mutation, 27 cases were heterozygous, and 41 cases were wild." (PMID 34895177, 2021). "Our findings suggest that after treatment with ATV or EFV, UGT1A1*28 and CYP2B6 c.516G>T (rs3745274) genetic polymorphisms influence the appearance of moderate-to-severe hyperbilirubinemia and CNS toxicity, respectively." (PMID 34093191, 2021). "Due to the poor development of the UGT1A1 enzymes that metabolize bilirubin in early life, newborns are prone to hyperbilirubinemia, and serious cases of hyperbilirubinemia can be life-threatening." (PMID 34034810, 2021). "Discovery of potent and safe UGT1A1 inducers will provide an alternative therapy for ameliorating hyperbilirubinaemia and drug-induced hepatoxicity." (PMID 33628187, 2020). "In Crigler-Najjar syndrome Type I, deleterious genetic lesions totally eliminate UGT1A1 activity and lead to potentially lethal hyperbilirubinemia." (PMID 32796590, 2020). "Unconjugated hyperbilirubinemia has been linked most consistently to the function of OATP1B1 and UGT1A1." (PMID 32796590, 2020). "Having efficient as well as safe UGT1A1 inducers for ameliorating hyperbilirubinaemia and drug-induced liver toxicity is one of the ways to overcome such medical problems." (PMID 33628187, 2020). "Based on current evidence, drugs that behave as mono- or multispecific inhibitors of OATP1B1, UGT1A1, and BSEP in vitro are at risk of causing clinically significant hyperbilirubinemia." (PMID 32796590, 2020). "In UGT1A1-normal subjects, homozygous variation c.521T > C increased total bilirubin level and the incidence of unconjugated hyperbilirubinemia compared to wild-type or heterozygous forms." (PMID 31737051, 2019). "Aside from UGT1A1, variants of SLCO1B1 have also been known to contribute to the severity of neonatal hyperbilirubinemia in Asian populations." (PMID 31253110, 2019). "Since xenobiotics used in clinical medicine are often associated with potentially severe side effects, natural compounds interfering with the UGT1A1 hepatic biotransformation system seem a better strategy to induce mild hyperbilirubinemia." (PMID 30891115, 2019). "We further showed that the circadian clock gene Bmal1 controlled the rhythmic expressions of Ugt1a1 and Mrp2 via direct transactivation, thus regulated the sensitivity of mice to chemical induced-hyperbilirubinemia." (PMID 31410205, 2019). "Five included trials compared the risk of hyperbilirubinemia between HIV-positive patients with a UGT1A1*28/*28 genotype and those with a UGT1A1*1/*28 or UGT1A1*1/*1 genotype." (PMID 30962262, 2019). "Relevant data for the comparison of the risk of hyperbilirubinemia between HIV-positive patients with a UGT1A1*28/*28 genotype and those with a UGT1A1*1/*28 genotype was available in four of the included trials." (PMID 30962262, 2019). "Approach and treatment of infants with hyperbilirubinemia and other UGT1A1-related drug therapies should be based on the considerations of SNPs specific for Southeast Asian populations." (PMID 31440488, 2019).
Hyperbilirubinemia (continued). "It was reported that a polymorphism of UGT1A1 gene promoter homozygous insertion of TA pairs (genotype UGT1A1*28/*28) might results in a decrease in bilirubin glucuronidation activity, leading to hyperbilirubinemia and late complication of patients with HS, such as development gallstones." (PMID 31122244, 2019). "We enrolled 60 patients from southeastern China (44 men and 16 women; age range: 3–76 years) with unconjugated hyperbilirubinemia and performed genetic analysis of the UGT1A1 gene by direct sequencing." (PMID 31467903, 2019). "Our results indicate that variants of UGT1A1 and/or SLCO1B1 have combined effects on Chinese adult mild unconjugated hyperbilirubinemia." (PMID 31737051, 2019). "The patient described here has unconjugated hyperbilirubinemia that is responsive to phenobarbital treatment and carries four genetic variations in the UGT1A1 gene, one of which is reported for the first time." (PMID 30285761, 2018). "Search of in-patient/out-patient records, and genetic test reports from January 2007 to December 2014 revealed 93 post-neonatal patients with unconjugated hyperbilirubinemia and UGT1A1 gene sequencing record." (PMID 30544479, 2018). "Gilbert’s syndrome is characterized by a chronic mild unconjugated hyperbilirubinemia with a normal liver function due to a 30% residual UGT1A1 activity." (PMID 29743555, 2018). "Our data demonstrate that G211 mutation in the UGT1A1 gene, ABO incompatibility, G6PD deficiency, and the SS genotype of the repeats in the promoter region of the HO-1 gene are risk factors for neonatal hyperbilirubinemia in Fujian, Southeastern China." (PMID 30298137, 2018). "Dose adjustments for hyperbilirubinemia have been described previously and it should be considered that this adverse effect is often temporary and a result of off-target inhibition of UGT1A1 by enasidenib." (PMID 30719396, 2018). "Functional defects in UGT1A1 result in unconjugated hyperbilirubinemia, which can be toxic to tissues if untreated and results in the characteristic jaundiced appearance." (PMID 28594959, 2017). "For instance, genetic lesions at the UGT1 locus that impair UGT1A1 expression or activity result in transient or fatal hyperbilirubinemia, characterizing Gilbert and Crigler-Najjar syndromes, respectively." (PMID 28217095, 2017). "To better characterize the nature of the hyperbilirubinaemia, we performed UGT1A1 genotyping of the human subjects." (PMID 26926838, 2016). "There was a significant correlation of neonatal hyperbilirubinemia with HO-1 promoter GT-repeat and nt211 in UGT1A1." (PMID 27557546, 2016). "Several antiretrovirals such as atazanavir or indinavir are related with unconjugated hyperbilirubinemia resulting to UGT1A1 inhibition similarly to that occurring in Gilbert's syndrome." (PMID 27065862, 2016). "There were greater risks of neonatal hyperbilirubinemia in infants with G6PD deficiency, short HO-1 promoter allele, and GA at nt211 in UGT1A1." (PMID 27557546, 2016). "Early intervention and close monitor are helpful in reducing severe hyperbilirubinemia for infants with G6PD deficiency, short HO-1 promoter GT-repeat, and GA at nt211 in UGT1A1." (PMID 27557546, 2016). "The contribution of polymorphism of the uridine-diphosphate-glucuronosyl transferase 1A1 gene (UGT1A1) to the severity of hyperbilirubinemia in these infants has also been reported." (PMID 27003893, 2016). "Details of promoter, exonic and splice site genetic variations in UGT1A1 gene identified in 71 Indian patients with unconjugated hyperbilirubinemia." (PMID 26716871, 2015). "Another SNP (rs6742078) in the UGT1A1 gene also showed a protective effect for neonatal hyperbilirubinemia." (PMID 26146841, 2015). "Mild unconjugated hyperbilirubinemia (UH), due to reduced activity of the enzyme uridine diphosphoglucuronate-glucuronosyltransferase family, polypeptide 1 (UGT1A1), is a common clinical condition." (PMID 26716871, 2015).
Hyperbilirubinemia (continued). "Several mechanisms have been proposed to explain the additive role of UGT1A1 gene variations and breastfeeding in significant neonatal hyperbilirubinemia." (PMID 26146841, 2015). "As for HO-1, the PPARα-dependent induction of UGT1A1 expression is pharmacologically relevant for the treatment of hyperbilirubinemia." (PMID 25147562, 2014). "The most common variant in UGT1A1 is a TA -insertion (TA6>TA7) in the promoter of UGT1A1, which is seen in individuals with low grade hyperbilirubinemias (Gilbert's syndrome, also called Gilbert-Meulengracht syndrome)." (PMID 24587300, 2014). "Hyperbilirubinemia frequently occurs among patients receiving ATV due to the inhibition of the UGT1A1 metabolic pathway, but its clinical consequences are usually limited to mild scleral icterus." (PMID 25409506, 2014). "In this paper, we intend to study the impact of A(TA)nTAA variation at the UGT1A1 gene promoter on hyperbilirubinemia and on the occurrence of cholelithiasis for the first time among SCA Tunisian children." (PMID 24167350, 2013). "Our studies indicate that PXR serves as a major regulator following glucocorticoid treatment by inducing liver UGT1A1 expression, leading to reduction of hyperbilirubinemia." (PMID 22371261, 2012). "Identification of PXR as a key regulator of the UGT1A1 gene during neonatal development can be exploited as a potential therapeutic target in the treatment of hyperbilirubinemia." (PMID 22371261, 2012). "RV expressing UGT1A1 injected in newborns or in conjunction with partial hepatectomy have achieved long-term correction of the hyperbilirubinemia in the Gunn rats." (PMID 19490653, 2008). "Crigler-Najjar syndrome (CNS) and Gilbert syndrome (GS) are inherited non-hemolytic unconjugated hyperbilirubinemias caused by mutations in the uridine diphosphate glucuronosyltransferase 1A1 (UGT1A1) gene, resulting in reduced or absent bilirubin conjugation." (PMID 41658774, 2026). "Studies in the humanized Gilbert’s syndrome mouse model, which has the UGT1A1*28 human gene locus and the mouse gene removed and exhibits mild hyperbilirubinemia, showed that when fed a high-fat diet, they had significantly less obesity, adiposity, and inflammation." (PMID 39873298, 2025). "This may be due to the inhibition of the organic anion transporter OATP1B1 and a glucuronosyltransferase, UGT1A1, induced by eltrombopag, which may lead to indirect hyperbilirubinemia." (PMID 40896456, 2025). "The frequencies of the A allele in UGT1A1-rs4148323 and the C allele in SLCO1B3-rs2417940 in the severe hyperbilirubinemia group (30.2% and 90.6%, respectively) were significantly higher than those in the controls (30.2% vs.13.0%, 90.6% vs. 78.0%, respectively, both p < 0.05)." (PMID 38279097, 2024). "CNS1 is the more severe form, characterized by a complete absence of UGT1A1 activity, leading to extreme unconjugated hyperbilirubinemia and a high risk of irreversible brain damage (kernicterus)." (PMID 39456788, 2024). "Additionally, sequencing the promoter region, particularly the TATAA box, is essential because the presence of a UGT1A1 polymorphism such as UGT1A128 (associated with GS) can further reduce the expression of the enzyme, exacerbating hyperbilirubinemia." (PMID 39456788, 2024). "In summary, a stepwise diagnostic approach for CNS includes the clinical assessment of jaundice, exclusion of other causes of hyperbilirubinemia, the trial of phenobarbital in suspected CNS2 cases, and confirmation through comprehensive molecular genetic testing of the UGT1A1 gene." (PMID 39456788, 2024). "Haplotype UGT1A1, UGT1A3, UGT1A7 and MDR1 3435 have been associated with hyperbilirubinemia." (PMID 36691090, 2023). "In addition, UGT1A1 211G>A was found to mildly exacerbate the severity of hyperbilirubinemia induced by ABO/Rh incompatibility, although the effect is not statistically significant." (PMID 38274110, 2023).